FOXP1 (forkhead box P1)
Diseases named in the same sentence as FOXP1 in open-access papers (continued):
Sharing a sentence is not in itself a finding about the gene and the disease.
tumor (continued). "Studies have found that FOXA1, FOXM1, FOXO3, FOXP1, and so on play an important role in tumors as oncogenes or tumor suppressor genes." (PMID 38608123, 2024). "Forkhead box protein 1 (FOXP1) serves as a tumour promoter or suppressor depending on different cancers, but its effect in oesophageal squamous cell carcinoma has not been fully elucidated." (PMID 38652109, 2024). "Forkhead-box protein P1 (FOXP1) has been proposed to have both oncogenic and tumor-suppressive properties, depending on tumor heterogeneity." (PMID 38279090, 2024). "Activation of the NAT10/FOXP1 axis in CC cells inhibits immune response by modulating glycolysis in tumor cells." (PMID 39640362, 2024). "As research into FOXP1’s functions has progressed, its critical involvement in various cancers and non-neoplastic diseases has become increasingly apparent." (PMID 39606233, 2024). "Among these were genes with putative tumor suppressor function in different cancer types including FOXP1, STK4,ATM, and others." (PMID 38464090, 2024). "Mechanistically, FOXP1 gene generally mapped to a tumor suppressor locus at 3p14.1, repressed AR-induced transcriptional activity or histone modification, and interacted between FOXP1 and NFAT1." (PMID 36952469, 2023). "To determine the FOXP1 downstream targets, we screened a series of genes that are critically important for tumor progression and highly correlated with FOXP1 expression." (PMID 36952469, 2023). "Overexpression of FOXM1, FOXC2 and FOXP1 have been shown to be important in tumor development, drug resistance, metastasis and poor prognosis in a variety of cancer types." (PMID 37401400, 2023). "After comparing the average expression of FOXP1 between tumor and normal tissue, an obvious increase in PC tissues is found as compared to the normal pancreatic tissues (P = 0.046)." (PMID 36952469, 2023). "Histopathology in high-FOXP1 expression was indicative of the massive cancer cell remission, including tumor nucleus fragmentation, deformation, cell disorder arrangement, coagulative necrosis and intercellular blank etc." (PMID 36952469, 2023). "FOXP1 promotes proliferation, tumor sphere formation, migration, invasion, and inhibition of anoikis." (PMID 37240338, 2023). "FOXP1 is a DNA-binding transcription factor that can act either as a tumor suppressor or as an oncogene." (PMID 37568789, 2023). "FOXP1 regulates the expression and transcriptional activity of many genes, which are involved in different stages of tumor, such as initiation, promotion and progression." (PMID 36952469, 2023). "Collectively, FOXP1 as a tumor suppressor inhibited PC progression by triggering the transcriptional activity of IRF1." (PMID 36952469, 2023). "Semi-quantitatively, we noticed that after the treatment with molecule 25, a decrease of FOXP1 immunoreactivity compared with the control was observed (p < 0.001), pointing to a role of this molecule in controlling tumor cells’ migration via FOXP1." (PMID 37568789, 2023). "In recent years, more and more scholars at home and abroad have proved the crucial role of FOXP1 in non-neoplastic diseases." (PMID 35043753, 2022). "FOXP1 is likely a tumor-suppressor gene in primary PCa, whereas the function of FOXA1 is context-specific." (PMID 36139541, 2022). "Overall, we show by CRISPR alteration that Foxp1 is a tumor suppressor by interfering with the AR pathway and Foxa1 is required for luminal cells’ identity." (PMID 36139541, 2022). "The infiltration abundances of Act CD4 and Tem CD8 in LUAD tumour tissue were negatively correlated with the expression of FOXP1, and FOXP1 was low in LUAD tissue." (PMID 36160018, 2022). "FOXP1 has been reported as a negative regulator of anti-tumor immune responses via its regulation on chemokine expression and MHC class II expression." (PMID 35449187, 2022). "The adenylate cyclase 5 gene, ADCY5, is thought to be regulated by the expression of FOXP1, a tumour suppressor." (PMID 35697697, 2022).
tumor (continued). "Testosterone ablation by castration impaired the tumor-suppressor function of Foxp1 and revealed Foxp1 as a negative regulator of AR-driven proliferation in the prostatic tissues." (PMID 36139541, 2022). "For instance, Foxp1 interacted with Smad2/3 and suppressed the tumor-reactive T cells’ response to TGF-β in advanced tumors." (PMID 36119068, 2022). "By applying CRISPR/Cas9, mutations have been introduced to the adult mouse prostate and it was revealed that Foxp1 acts as a tumor-suppressor gene by controlling proliferation in an androgen-dependent manner." (PMID 36139541, 2022). "Known exceptions that can be considered driver events include promoter and enhancer rearrangements such as known for AR and FOXP1, but also tumour suppressor gene deletions." (PMID 34891161, 2021). "To assess the contribution of Nfib and Foxp1 to tumour growth and metastatic progression, we produced knockout (KO) cells for the two genes using CRISPR‐Cas 9 technology in the highly metastatic LM1 and LM9 lines and generated oligoclonal pools of cells." (PMID 33751828, 2021). "We further analysed these 249 FoxP1 targets repressed in response to tumour burden using Gene Set Enrichment Analysis and the Molecular Signatures Database to identify conserved transcription factor binding motifs commonly shared among their gene promoters." (PMID 33527776, 2021). "Knockdown of FoxP1 partially attenuated muscle fibre atrophy induced by tumour burden and visually improved muscle ultrastructure as observed via TEM." (PMID 33527776, 2021). "We previously identified, through an unbiased microarray analysis, that FoxP1 is a downstream target of FoxO, which is increased in the skeletal muscle of C26 tumour‐bearing mice." (PMID 33527776, 2021). "Eosinophilia-specific PDGFRA-fusion with FOXP1 disrupts this gene, supporting tumor suppressor activity in this malignancy." (PMID 33048949, 2020). "They finally determined that five out of the seven mRNA, i.e. Apbb1ip, Aspn, Incenp, Daf2, and Foxp1, were significantly upregulated (p < 0.05) in saliva-derived exosomes of tumor-bearing mice." (PMID 33297544, 2020). "This patient’s tumour is characterized by KMT2C mutation, copy number losses (supported by large deletion) in PTEN and FOXP1 and an ETV1-ACSL3 fusion." (PMID 32392735, 2020). "Previous studies show that high expression of NR4A2, BTNL9, FOXP1, or PDE4D can antagonize immune response or is associated with tumor progression." (PMID 30911684, 2019). "Genes with a tumor suppressive role including FOXP1 and FGFR2 were downregulated in both cell groups." (PMID 31013771, 2019). "Compared to those of naive mice spleen CD8+ T cells, the levels of PD-1, TIM-3, BTLA and Foxp1 were upregulated in tumour-bearing mice." (PMID 31594465, 2019). "For instance, FOXP1 induction by inhibition of miR-9 promoted tumor growth, while FOXP1 knockdown suppressed the growth of epidermal growth factor receptor (EGFR) dependent cancers." (PMID 31815635, 2019). "LINC01614 and FOXP1 were found to be up‐regulated in LUAD tumours and cells, whereas miR‐217 was down‐regulated." (PMID 29934982, 2018). "FOXP1 is generally considered a transcriptional repressor and is a tumor suppressor in epithelial malignancies such as lung cancer and breast cancer." (PMID 30360388, 2018). "In contrast, our xenograft analysis of FOXP1-depleted MCF7 cells clearly showed a retardation of tumour growth." (PMID 29876520, 2018). "In vivo studies using the transduced cell lines in mice enabled us to demonstrate a tumor suppressor effect of miR-92a and an oncogenic effect of FOXP1." (PMID 27806315, 2017). "A recent study indicated that FoxP1 expression was required for TGFβ-mediated inhibition of anti-tumor CD8+ T cells." (PMID 29116089, 2017). "The work presented here establishes that the 3p13-14 locus from FOXP1 to SHQ1 has tumor suppressor activity in the context of PI3K pathway activation conferred by PTEN loss." (PMID 29057879, 2017).
tumor (continued). "In GBM cells with EGFR mutation, which is occurring in large proportion of patients, miR-9 is identified as a tumor suppressor which is regulated by FOXP1." (PMID 28868238, 2017). "Given that FOXP1 has been proposed to function as a tumor suppressor in the breast, we wanted to determine the effect of FOXP1 on MCF7 growth." (PMID 29262329, 2017). "The winged helix transcription factor Forkhead box P1 (FOXP1) has been reported to function as either oncogene or tumor-suppressor in various cancers." (PMID 26654944, 2016). "The time course follow-up of tumor volume showed that tumors from A2780 cells with FOXP1 knockdown were consistently smaller than tumors from control A2780 cells during development." (PMID 26654944, 2016). "FOXP1 plays an important role during pathologic tumor development by potentiating Wnt/β-catenin signaling in DLBCL38." (PMID 27457567, 2016). "Western blot analysis, tumor xenograft models, and flow cytometry analysis were performed to elucidate the function of FOXP1 in the regulation of cell proliferation in human HCC." (PMID 27618020, 2016). "As inferred from our results, CD8+ NTeff are less influenced by tumor-derived inhibitory factor TGF-β, i.e., effectors derived from naïve cells are less affected by tumor suppression mechanisms driven by Foxp1 in response to TGF-β." (PMID 27306834, 2016). "To determine the immunosuppressive resistance potential of CD8+ NTeff cells in the tumor microenvironment, we examined expression of Foxp1 among effector cells derived from naïve, memory, and TIL progenitors in the presence of TGF-β." (PMID 27306834, 2016). "Our results demonstrate that tumor-suppressive effects of FOXP1 inhibit epithelial cell proliferation, which can be counteracted with EBV-miR-BART11 expression." (PMID 27167345, 2016). "FOXP1 is known to function as a tumor suppressor or an oncogene in different human cancer types depending on the cellular context." (PMID 26654944, 2016). "Our results demonstrated that EBV-miR-BART11 plays a crucial role in the promotion of inflammation-induced NPC and GC carcinogenesis by inhibiting FOXP1 tumor-suppressive effects." (PMID 27167345, 2016). "FOXP1 has been identified as having diverse functions, and can act as either a tumor suppressor or an oncogene." (PMID 27618020, 2016). "The tumor xenograft models also confirmed that FOXP1 is a positive regulator of tumorigenicity in HCC." (PMID 27618020, 2016). "In this system, Foxp1 blocks anti-tumor function of murine TIL through transcriptional control of AP-1 complex formation, interacts in the nucleus with SMAD2/3, and is required for inhibition of CD8+ T cell function by TGF-β." (PMID 26393659, 2015). "We found that FOXP1 was upregulated in tumor tissues compared to adjacent normal tissues." (PMID 40169859, 2025). "FOXP1 was highly expressed in tumor tissues, as well as LEF1 and OCT4, which are markers of CSCs." (PMID 40169859, 2025). "Not recognised as a PCa germline testing panel gene, forkhead box P1 (FOXP1) is an established PCa tumour suppressor driver gene, with CN loss increasing cell proliferation and migration, and poor prognosis." (PMID 40064858, 2025). "Moreover, the inhibition of FOXP1 in orthotopic mouse models reduced tumor growth and proliferation, and enhanced sensitivity to gemcitabine." (PMID 40169859, 2025). "FoxP1-dependent DEGs identified above in skeletal muscle of KPC tumor-bearing mice may reflect both direct and indirect targets regulated by FoxP1." (PMID 40349340, 2025). "However, emerging data support that FOXP1 has dual functions as both a tumor suppressor and oncoprotein in the context of different cancers." (PMID 39623140, 2025). "FOXP1 drove tumor progressions in osteosarcoma and bladder cancer." (PMID 40169859, 2025). "Furthermore, the study observed a shift in FOXP1 localization from the nucleus to the cytoplasm with increasing tumor malignancy, suggesting reduced nuclear FOXP1 expression and increased cytoplasmic staining." (PMID 40746724, 2025).
tumor (continued). "In vitro, functional studies demonstrated tumor-promoting effects of FOXP1 in AML." (PMID 40672953, 2025). "FOXP1 was previously reported as having both tumor-suppressive and oncogenic roles." (PMID 40169859, 2025). "This study revealed the anticarcinogenic effect of FOXP1 in oesophageal squamous cell carcinoma, which may serve as a novel biological target for the treatment of tumour." (PMID 38652109, 2024). "FOXP1 has been identified as a tumor suppressor in several BRCA-related studies." (PMID 38608123, 2024). "This appears to be consistent with the role of FOXP1 as a tumor suppressor." (PMID 38608123, 2024). "We also found that putative tumor suppressors, such as FOXP1, STK4, and ATM were frequently hypermethylated and silenced whereas oncogenes, such as UHRF1, MPZL1, CDK14, RACGAP1, and RAB13, were hypomethylated and overexpressed suggesting that DNA methylation changes contribute to PTCL development." (PMID 38464090, 2024). "Not recognised as a PCa germline testing panel gene, FOXP1 is an established PCa tumour suppressor driver gene, with CN loss increasing cell proliferation and migration, and poor prognosis." (PMID 38947031, 2024). "This further indicates that FOXP1 may participate in the regulation of tumour immune infiltrating cells by regulating the expression of chemokine family related proteins, thereby inhibiting the growth of oesophageal squamous cell carcinoma cells." (PMID 38652109, 2024). "Moreover, the animal study demonstrated that depletion of FOXP1 significantly increased the tumor growth rate, and FOXP1 upregulation exhibited the opposite trend when compared with the control group." (PMID 38279090, 2024). "Our findings suggest that FOXP1 may serve as a novel outcome predictor for ICC as well as a tumor suppressor that may contribute to cancer treatment." (PMID 38279090, 2024). "We also analysed the correlation between FOXP1 and tumour immune infiltration levels." (PMID 38652109, 2024). "We speculated that FOXP1 may regulate different immune infiltrating cells depending on different tumours." (PMID 38652109, 2024). "Furthermore, the IHC results revealed an upregulation of the Foxp1 level in the tumor tissues after anti-CD47 Ab treatment." (PMID 38398223, 2024). "Particularly in BC, FOXP1 overexpression was related to tumor proliferation." (PMID 37568789, 2023). "The discrepancy may be attribute to the dual role of FOXP1 in PC, tumor-promoting and tumor-suppressive function." (PMID 36952469, 2023). "Moreover, SiHa tumor xenografts established from cells with NAT10 deficiency showed significantly decreased staining for NAT10, FOXP1, GLUT4, and KHK." (PMID 37818745, 2023). "FOXP1 upregulation inhibited tumor cell growth, whereas FOXP1 knockdown had a opposite result." (PMID 36952469, 2023). "Collectively, these data underscore the oncogenic function of upregulated FOXP1 in CCa malignant progression; thus, FOXP1 upregulation could ameliorate the tumor‐suppressive effect of NAT10 depletion in CCa cells." (PMID 37818745, 2023). "In summary, we unveiled that FOXP1 acted as a tumor suppressor in PC progression." (PMID 36952469, 2023). "Interestingly, FOXP1 plays an important role in the prognosis of cancer patients, acting as a tumor suppressor in some tumors but a cancer driver in others." (PMID 36952469, 2023). "To date, it is still unclear whether FOXP1 protein works as an oncogenic or tumor suppressive role in PC." (PMID 36952469, 2023). "miRNAs: miR-181d-5p acts as a tumor suppressor in OS by targeting FOXP1." (PMID 37240338, 2023). "Consistent with tumor volume, the tumor weights further demonstrated that FOXP1 expression could hinder tumor growth." (PMID 36952469, 2023). "Although additional work is needed to expand our knowledge, there is already growing evidence that FOXP1 may play an important role in T-cell exhaustion, affecting T-cell ability to fight tumor." (PMID 36268015, 2022).
tumor (continued). "IHC and ISH experiments conducted using mice subcutaneous tumor tissue sections showed that FOXP1 and PBRM1 expression was significantly lower and that for PD-L1 was significantly higher in the BART11+BART17-3p and BART11+BART17-3p+ T cells group than those in the NC and NC+ T cells groups." (PMID 35165282, 2022). "(2014) analyzed FOXP1 in the context of TGF-β signaling in the tumor microenvironment." (PMID 36268015, 2022). "Similarly to human TILs, FOXP1 expression was higher in CD8+ T-cells from a tumor-bearing mouse supporting its role in T-cell exhaustion." (PMID 36268015, 2022). "We therefore determined whether FoxO1 is sufficient to increase FoxP1 transcription and required for its up‐regulation in response to tumour burden." (PMID 33527776, 2021). "Based on our current knowledge of the role of FoxP1, coupled with its concomitant increase in the skeletal muscle of mice bearing atrophy‐inducing tumours, we hypothesized that FoxP1 is a key mediator of cancer‐induced skeletal muscle wasting." (PMID 33527776, 2021). "Our genomic profiling data showed a small deletion at 3p13 targeting the 3 ́-part of FOXP1 which may underlie reduced expression levels in EOL-1, indicating tumor suppressor activity for this gene." (PMID 33048949, 2020). "Also, downregulation of FOXP1 increased miR-34a level as a tumor suppressor in gastric diffuse large B-cell lymphoma (gDLBCL) cells." (PMID 31815635, 2019). "An additional study has shown that miR-34a reduces tumor growth in mice by targeting Foxp1." (PMID 31472685, 2019). "The transcriptional repressor FOXP1 has been defined as a tumor suppressor in several cancers." (PMID 31118037, 2019). "This relationship was further confirmed by the negative correlation between LEF1-AS1 expression and FOXP1 expression, which is a well-known effector of miRNAs, Silencing LEF1-AS1 also significantly increased miR-544a expression, downregulated FOXP1 expression, lower tumor size and Ki-67 expression." (PMID 30734202, 2019). "Similarly, FOXP1 represses AR-induced transcriptional activity or histone modification as a tumor suppressor." (PMID 31815635, 2019). "The expression level of FOXP1 was higher in tumor samples than normal samples." (PMID 31235696, 2019). "Several members of this family, such as FOXA1 and FOXP1, may be either oncogenic or tumor-suppressive depending on how they interact with the distinct transcriptional networks of tissue-specific cancers." (PMID 30360388, 2018). "The recent study of whole-genome sequences of 57 primary prostate tumors highlighted NKX3-1 and FOXP1 loss, and TMPRSS2–ERG fusion as highly clonal, meaning that these events occur very early in tumor development and are probably important for tumor initiation." (PMID 29734647, 2018). "On the other hand, FOXP1 might attenuate tumorigenicity to exert a tumor-suppressive effect in other tumors, such as neuroblastoma and prostate cancer." (PMID 29848352, 2018). "Meanwhile, further experiments such as whether FOXP1 does indeed act as a tumour suppressor in LUAD are in need." (PMID 29934982, 2018). "Recently, the EGFRvIII/Ras/PI3K/AKT axis has been shown to exert its tumorigenic influence through the specific inhibition of miR‐9 leading to the up‐regulation of the transcription factor FOXP1, thus providing a tumor growth advantage to EGFRvIII‐driven tumors." (PMID 28248456, 2017). "More significantly, depletion of FOXP1 in xenografts significantly reduced tumor growth." (PMID 29262329, 2017). "Similarly, this contradiction is also demonstrated in the prognostic value of FOXP1 protein expression in tumor patients." (PMID 27457567, 2016). "However, we did not comprehensively evaluate the prognostic impact of overexpressed FOXP1 protein in the tumor patients." (PMID 27457567, 2016). "All of these observations indicate that the FOXP1 protein may have a specific prognostic value for tumor patients." (PMID 27457567, 2016).